LEP (leptin)
Diseases named in the same sentence as LEP in open-access papers (continued):
Sharing a sentence is not in itself a finding about the gene and the disease.
steatosis (continued). "On the other hand, the AUC value of the combination of miR-126-5p and leptin in the diagnosis of steatosis was 0.950 in one of the recent studies." (PMID 39857813, 2025). "The best predictor value for steatosis was obtained by combining miR-126-5p with leptin, presenting an AUC of 0.95." (PMID 39138826, 2025). "Leptin replacement therapy in these patients leads to improvements in liver histology, with significant reductions in steatosis, inflammation, and hepatocellular injury." (PMID 40956476, 2025). "The average values of leptin were 22.3 ± 14.1 ng/mL, 22.77 ± 13.19 ng/mL in patients with steatosis and 25.47 ± 14.33 ng/mL in fibrotic ones." (PMID 40507178, 2025). "Leptin levels, indicative of adipose tissue mass, showed a progressive increase from the control group (HC) to simple steatosis (SS) and further to steatosis with fibrosis (SF), with median values of 10, 20.5, and 21 ng/mL, respectively." (PMID 38738048, 2024). "With good sensitivity and moderate specificity, leptin is a significant predictor for steatosis in the NAFLD spectrum of the disease." (PMID 38738048, 2024). "Leptin shows anti-steatosis effects in the early stages of NAFLD, which are mediated via fatty acid oxidation and a reduction in lipogenesis." (PMID 38247213, 2024). "The cut-off value of 12.2 ng/mL showed 70% sensitivity and 50% specificity for steatosis, while at a threshold of 18 ng/mL, leptin demonstrated 40% sensitivity and specificity for fibrosis." (PMID 38738048, 2024). "The optimal cutoff value for serum leptin in predicting the occurrence of steatosis in our study was determined to be 12.2 ng/mL, yielding a sensitivity of 70% and specificity of 50%, with an AUROC of 0.67 and p-value of < 0.001." (PMID 38738048, 2024). "High-fat diet provokes increased hepatic lipogenesis and inflammation, reduced fatty acid oxidation, and inflammation, with higher hepatic leptin levels and steatosis in mice." (PMID 36674935, 2023). "The leptin knockout mice, Lepob/Lepob (ob/ob), are obese, insulin resistant, and hyperglycemic, and show some degree of steatosis." (PMID 37377968, 2023). "A positive correlation has been established between elevations in circulating leptin in non-alcoholic fatty liver disease patients, steatosis patients, as well as non-alcoholic steatohepatitis patients (NASH)." (PMID 35628271, 2022). "Within the liver, leptin is considered an anti-steatosis hormone, but the levels and duration matters." (PMID 35628271, 2022). "In patients with non-alcoholic fatty liver disease (NAFLD), leptin levels increase in line with the steatosis severity." (PMID 36075960, 2022). "Further, treatment with MJM60958 also reduced steatosis scores in liver tissues, serum leptin and interleukin, and increased serum adiponectin content." (PMID 36362221, 2022). "Serum FGF19 and adiponectin-to-leptin ratio (A/L) were negatively correlated with steatosis, consistent with previous findings." (PMID 35663311, 2022). "For example, leptin reverses steatosis through SREBP/mTOR inhibition, while also promoting liver inflammation and fibrosis in non-parenchymal cells." (PMID 35355551, 2022). "Leptin levels are positively correlated with steatosis severity, whereas it is unclear between leptin levels and the progression of inflammation and fibrosis." (PMID 33925827, 2021). "The effects found in mothers which did not receive fructose (FC) were so impressive that fructose ingestion by these pregnant offspring (FF) was only able to produce a slightly higher severity, in terms of leptin function and steatosis." (PMID 34684668, 2021). "This included a reduction in total cholesterol, low-density lipoprotein-c, and leptin levels, when compared with the steatosis control." (PMID 33339155, 2020). "The steatosis observed in ob/ob mice suggests that leptin is taken up by the fatty liver, indirectly owing to central nerve pathways and directly by hepatic AMPK activation." (PMID 33324348, 2020).
steatosis (continued). "Serum leptin level was statistically different over different grades of steatosis in ultrasound (F = 8.698, P < 0.001)." (PMID 32728230, 2020). "We demonstrate that brain leptin protects from steatosis by promoting hepatic triglyceride export and decreasing de novo lipogenesis independently of caloric intake." (PMID 31222048, 2019). "Leptin significantly reduced the weight and triglyceride content in the liver and improved steatosis in OSI-906-treated mice." (PMID 28646158, 2017). "Patients with simple steatosis and NASH exhibited higher serum levels of leptin compared to controls and high leptin concentrations were associated with increased severity of NAFLD." (PMID 28758929, 2017). "IL-6 administration in DIO mice markedly raised circulating levels of lipids, glucose and leptin, elevated fat liver content and aggravated steatosis." (PMID 27333268, 2016). "The present study shows the effect of KBH-1 in the treatment of steatosis and liver and accompanying leptin resistance in the hypothalamus through continuous feeding with a HFD for up to 15 weeks." (PMID 27618865, 2016). "After 2 months, HFHF and HFD increased body weight, leptin, HOMA2-IR associated to steatosis, oxidative stress in plasma and tissues, whereas HF had only a transient increase of leptin and c-peptide." (PMID 26918024, 2016). "Fish oil, a source of PUFA has been shown to ameliorate CLA-induced steatosis by increasing leptin and adiponectin levels and decreasing plasma insulin." (PMID 21869929, 2012). "Other studies have shown that leptin levels appear torise as hepatocyte steatosis develops." (PMID 41165450, 2025). "The adiponectin/leptin (A/L) ratio has been suggested as a marker of adipose tissue dysfunction, also known as secretory adiposopathy, characterized by altered lipid metabolism, and a more accurate index for steatosis lesions and their progression to MASH." (PMID 40299427, 2025). "Finally, the major value for predict the presence of steatosis was obtained combining miR-126-5p with leptin (model 7) obtaining an AUC of 0.95." (PMID 39138826, 2025). "Together, it seems plausible that an as-yet-unknown bioactive component of beans may result in an improvement in leptin sensitivity with direct protective implications for liver lipid signaling and steatosis." (PMID 38613062, 2024). "Therefore, patients with higher circulating leptin levels had a possible beneficial effect on steatosis." (PMID 39201901, 2024). "Interestingly, around the same age, 60% of LEPTIN−/− pig livers displayed lipid deposition and hepatocyte steatosis." (PMID 37705071, 2023). "Lepr has been reported as a possible target gene being upregulated by metformin which may enhance leptin sensitivity in the liver to alleviate steatosis." (PMID 37727633, 2023). "On the one hand, low folate diets lead to steatosis in the liver of mice, secondary to altering a number of enzymes controlling the methylation cycle, promotes lipid accumulation and leptin production of adipocytes, and even provokes subsequent cognitive dysfunction in mice." (PMID 36830876, 2023). "Administration of leptin reverses the obese phenotype and improves steatosis." (PMID 37377968, 2023). "In this regard, leptin should have an anti-steatosis impact on hepatocytes." (PMID 37400922, 2023). "Those deficient in leptin develop steatosis more frequently, but do not spontaneously develop fibrosis since leptin is a mediator for its development." (PMID 36674935, 2023). "Serum leptin levels are increased in both patients with NAFLD and in animal models of the disease and may be associated with the development of hepatocyte steatosis and its progression through OB-R (leptin receptor) activation of the PI3-K/Akt kinase pathway." (PMID 35405942, 2022).
steatosis (continued). "Multivariate regression showed that waist-to-hip ratio, fibroblast growth factor (FGF) 21, FGF19, adiponectin-to-leptin ratio, insulin, albumin, triglyceride, total-cholesterol, and alanine-aminotransferase were independent predictors of steatosis (rank-ordered by Wald)." (PMID 35663311, 2022). "Microscopic observation of liver sections confirmed the presence of microvesicular steatosis in the liver of the HF-fed groups; smaller lipid vacuoles could be visually observed in the HF-Leptin group, consistent with the lower total fat content." (PMID 35684076, 2022). "The z-scores of circulating leptin levels declined with increasing severity of steatosis hepatis." (PMID 35677722, 2022). "Interestingly, these mice developed more steatosis when challenged with HFD owing to the loss of histamine/leptin signaling, leading to leptin resistance." (PMID 34440841, 2021). "In this sense, the physiological role of leptin in the liver was known before this adipokine was discovered, as both db/db and ob/ob mice were shown to present alterations in the liver function, including steatosis." (PMID 34209386, 2021). "Only one study pointed out leptin and adiponectin as markers of steatosis reduction." (PMID 35010923, 2021). "On the other hand, C57BL/6 mice subjected to a western diet for six weeks to induce simple steatosis present an improvement of hepatic regeneration after partial hepatectomy that correlates with the increase of the leptin presence in serum among other signaling factors." (PMID 33316927, 2020). "Methyl donor supplementation during the perinatal period reduced leptin secretion in rat offspring, while supplementing methyl donors to HF-fed or high-fat-sucrose-fed dams protected offspring from increased weight gain, adiposity, and steatosis." (PMID 31947955, 2020). "Resveratrol and NAC administration significantly improved liver index (resveratrol only), alanine transaminase, TNF-α, glucose, albumin, malondialdehyde (MDA), GSH, glutathione-S-transferase, total cholesterol, low-density lipoprotein-c, and leptin levels compared with steatosis control values." (PMID 33339155, 2020). "Leptin can also promote the development of liver fibrosis, steatosis, and pro-inflammatory." (PMID 33256658, 2020). "The probiotic mixture showed promise as a treatment for NAFLD pathogenesis, and may improve HFSD-induced steatosis through its effects on leptin, resistin, inflammatory biomarkers, and hepatic function markers." (PMID 28086768, 2017). "In addition, the aim of this study is to identify the effect of KBH-1, standardized herbal composition, on steatosis and leptin resistance." (PMID 27618865, 2016). "Although this data was not assessed in our population due to a low prevalence of significant steatosis (only 11 out of 75 patients had steatosis in more than 5% of hepatocytes) a slight increase of serum leptin in female with higher degree of steatosis was observed." (PMID 25821463, 2015). "Elevated leptin levels have been reported in patients with chronic HCV infection, and especially in those with metabolic risk factors, but it seems to be directly related to the degree of steatosis and of fibrosis." (PMID 25821463, 2015). "Histological sections of leptin-deficient ob/ob mice were characterized by the presence of severe macrovesicular steatosis, but not advanced inflammation/fibrosis, that was completely reverted after leptin administration for 28 days." (PMID 26159457, 2015). "Steatosis can increase formation of proinflammatory and profibrogenic cytokines and leptin, which may contribute to development of hepatitis and fibrosis." (PMID 24618581, 2014). "Our findings suggest that NHANES III-derived RLD thresholds are not effective for identifying steatosis risk groups in unselected populations, where they appear to capture metabolically healthy individuals rather than those with pathological leptin insufficiency." (PMID 40956476, 2025).
steatosis (continued). "Leptin is an adipokine that has different effects on MASLD progression: in the early stages of the disease, it has a protective role against steatosis by preventing hepatic lipid accumulation, but as the disease progresses, leptin could have a proinflammatory and profibrogenic role." (PMID 41373837, 2025). "However, in vivo studies do not support a causal association since ob/ob mice that lack leptin and develop hyperphagic obesity have severe steatosis." (PMID 37377968, 2023). "However, leptin resistance with a high level of leptin in serum may be a feature of steatosis that contributes to the development of NAFLD." (PMID 36362221, 2022). "Chow-fed control mice did not have a similar effect and leptin increased hepatic expression of CD14 via STAT3 signaling and hyperreactivity against low-dose LPS without steatosis, while leptin-deficient ob/ob mice with severe steatosis had a marked decrease in hepatic CD14." (PMID 35052763, 2021). "Thus, enhanced expression of hepatic CD14 by leptin may increase hepatic responsiveness to gut microbiota-derived endotoxins even at low levels, resulting in the progression from simple steatosis to NASH via STAT3 signaling." (PMID 34360923, 2021). "Thus, we can suppose that higher hepatic leptin sensitivity might contribute to the lower level of steatosis and serum triglyceride level detected in HFD-fed females as opposed to males." (PMID 33919597, 2021). "However, LE supplementation noticeably attenuated the extent of steatosis, suggesting that LE may regulate lipid storage and mobilization in adipocytes by modulation of the leptin level." (PMID 23365609, 2013). "For this purpose, we evaluate the clinical significance of leptin, vitamin D, APRI, and FIB-4 in cirrhotic patients with different ratios of steatosis and in cirrhotic pateints with different grades of hepatocellular carcinoma." (PMID 41721256, 2026). "Likewise, the roles of adipose tissue reserve and leptin in the defense against infection may differ among patients with marasmus, who have severe generalized wasting, and kwashiorkor, who are more likely to have steatosis and preservation of muscle mass." (PMID 40944251, 2025). "Much evidence indicates that LEPR serves as a novel biomarker for leptin sensitivity, and the augmentation of LEPR is related to the reduction of steatosis." (PMID 37727633, 2023). "The main outcomes of this study include, but are not limited to, an alleviation of hepatocyte steatosis and an increased level of glucagon-like peptide-1 (GLP-1) in serum, as well as decreased leptin and IR in these mice." (PMID 35454311, 2022). "Despite improving leptin signaling in the hypothalamus and enhancing insulin sensitivity in HFD-fed mice, Lobe increased body weight and steatosis." (PMID 29979770, 2018). "Most obese humans, with steatosis and/or NASH, present elevated serum leptin levels, because of leptin resistance." (PMID 24829591, 2014). "The insulin sensitizing action of leptin and adiponectin normalizes insulin levels which further helps in preventing CLA-induced steatosis." (PMID 21869929, 2012). "In a recent study, using the combination of HOMA-IR with the adiponectin/leptin ratio, the AUROC was 0.82 for distinguishing between NASH and simple steatosis." (PMID 22110476, 2012). "In binary logistic regression analysis, the biologics (group), disease activity, disease duration, age, adiponectin, TNF, leptin, PIIINP, and TIMP-1 were sequentially entered as potential confounders, with the dependent variable being the presence of steatosis, based on the Hamaguchi score." (PMID 39598344, 2024). "For instance, compared to Zeb1WT/ApoeKO mice, Zeb1∆M/ApoeKO mice had higher body weight, greater steatosis, higher WAT immune infiltration, higher serum levels of pro-inflammatory markers (IL1β, IL2, IL12, leptin, CCL2), higher cholesterol and LDL, and lower HDL and glucose tolerance." (PMID 38097578, 2023).
steatosis (continued). "Leptin depletion was significantly correlated with higher organ radiodensity, higher WAT cell density, lower BAT lipid droplet %, lower macro-vesicular and total steatosis, and higher liver portal inflammation at both 8 and 14 months of age." (PMID 35448465, 2022). "The level of leptin significantly increased in the serum of patients with NAFLD and in animal models of the disease and possibly normalized with the development of hepatocyte steatosis." (PMID 34988225, 2021). "In chow-fed mice Leptin increased hepatic expression of CD14 via STAT3 signaling and hyperreactivity against low-dose LPS without steatosis, while leptin-deficient ob/ob mice with severe steatosis had a marked decrease in hepatic CD14." (PMID 32823983, 2020). "Serum leptin level was significantly higher in patients with grade 2 steatosis (28.74 ± 28.68 ng/ml) and grade 1 steatosis (18.37 ± 20.54 ng/ml) compared to the patients without steatosis (10.29 ± 11.53 ng/ml)." (PMID 32728230, 2020). "The histological examination supported the results of the serum biochemical analysis: ob/ob liver sections exhibited macrovesicular steatosis that was completely reversed after leptin administration for 28 days, but not by caloric restriction." (PMID 30818874, 2019). "Ob/ob- and db/db mice lacking leptin and the leptin receptor, respectively, are hyperphagic and consequently develop all symptoms of the metabolic syndrome and steatosis already with regular chow diet." (PMID 28207798, 2017). "In the HIV-Tg rats, binge alcohol increases LPS/endotoxin-mediated hepatic leptin and TLR4 level, which further activated Kupffer cells with up-regulated levels of MCP-1 and CCR2, at least partially, contributing to greater hepatic inflammation and steatosis." (PMID 26484872, 2015). "Leptin-deficient mice, a murine model of NAFLD, displayed macrovesicular steatosis without changes in hepatic AQP9 mRNA and protein." (PMID 26159457, 2015). "At a threshold of 18 ng/mL, leptin demonstrated a sensitivity and specificity of 40% each in predicting the presence of fibrosis in NAFLD and the curve showed limited discriminatory power when distinguishing between steatosis and fibrosis (AUROC = 0.52 and p-value = 0.76)." (PMID 38738048, 2024). "Furthermore, this ratio was able to discriminate between severe and mild steatosis, whereas adiponectin or leptin alone were not." (PMID 35663311, 2022). "Enhanced expression of leptin-induced hepatic CD14 may increase hepatic responsiveness to even low levels of gut microbiota-derived endotoxins, which may prompt the progression of simple steatosis to NASH via STAT3 signaling." (PMID 34777261, 2021). "For example, women with obesity with high levels of leptin develop resistance to its effects rather than sensitivity, showing a positive correlation with serum insulin levels, insulin resistance, and liver damage, including both steatosis and inflammation, contributing to MASLD/MASH." (PMID 40299427, 2025). "Consequently, leptin is capable of inducing inflammation and fibrosis without existing steatosis." (PMID 33316927, 2020). "In regression analyses, none of the chosen eight predictors (BMI, HOMA-IR, steatosis grade, ballooning grade, VAT OXPHOSmax, plasma leptin, plasma adiponectin and alanine aminotransferase) were found to be significantly associated with liver OXPHOSmax per CS." (PMID 35614135, 2022). "In our experimental model, steatosis induced by CAF diet and fat content of cells have been extensively analyzed in a precedent study; however, markers like adipokines (leptin, adiponectin) have not yet been evaluated." (PMID 30884780, 2019). "Leptin and STAT3 signaling increased the responsiveness to gut-derived, low-dose bacterial endotoxin even in the healthy liver via an increase in CD14-positive Kupffer cells, regardless of the presence of steatosis." (PMID 34360923, 2021).